S100A8 (S100 calcium binding protein A8)
Diseases named in the same sentence as S100A8 in open-access papers (continued):
Sharing a sentence is not in itself a finding about the gene and the disease.
COVID-19 (continued). "Collectively, PIRAT down-regulation and LUCAT1 up-regulation in monocytes in this model fuels the expression of S100A8 and S100A9, which contribute to myeloid imbalances during severe COVID-19." (PMID 35998224, 2022). "Gene expression of IFITM1 in neutrophils from patients with COVID-19 at t1 was confirmed by immunofluorescent staining for IFITM1 protein, co-localized with S100A8/9, and typical neutrophil nuclear morphology." (PMID 34782790, 2022). "Levels of the inflammasome cytokine IL1B, the neutrophil chemotaxis factor CXCL8, and alarmins S100A8 and S100A9 were comparably elevated in KD and severe COVID-19 compared to FC and HC, respectively." (PMID 36159873, 2022). "For example, S100A8, S100A9, and S100A12 levels in blood have recently been shown to correlate with disease severity in COVID-19 patients infected with SARS-CoV-250,51." (PMID 35396513, 2022). "Meanwhile, CXCL8, S100A8, S100A9, S100A12, FCGR1A, PADI4, and BCL2A1 showed significant increases in severe COVID-19 when compared with mild COVID-19 (p <0.05)." (PMID 36159873, 2022). "Some features such as IFI44L in B cells, S100A8 in monocytes, and NCR2 in natural killer cells are involved in the innate immune response of COVID-19." (PMID 35928229, 2022). "This notion was further corroborated in qRT-PCR and FACS validations, which confirmed the control of S100A8, S100A9, ITGAX, and IRF5 by PIRAT and regulation of these factors during COVID-19." (PMID 35998224, 2022). "There was a highly overlapped rate of these up-DEGs between moderate and severe COVID-19 groups, including ACP1, S100A8, and A100A9 (18/20 = 90%)." (PMID 35172892, 2022). "The alarmins S100A8/S100A9 are ranked among the top DEGs increased in progressive vs stable monocytes, as also shown by recent scRNA-seq COVID-19 studies, and as observed in SARS-CoV infection." (PMID 35064122, 2022). "Only levels of IL1B, neutrophil chemotactic CXCL8, and alarmins S100A8/S100A9 were comparably elevated in KD and COVID-19 compared to their respective controls." (PMID 36159873, 2022). "In particular, a number of TSPs such as S100A8/9, UMOD and NRGN were also significantly up-regulated in COVID-19 post-mortem tissues." (PMID 34876996, 2021). "We also measured the epithelial cell–derived biomarkers S100A8, regenerating islet-derived protein 3 alpha (REG3A), and IL-1α and found both S100A8 and REG3A levels to be modestly increased in COVID-19 patients relative to HVs across all severity categories." (PMID 33232303, 2021). "Expression of the S100A8/A9, members of the S100 family, and the IL6 co-receptorIL6ST was elevated in COVID-19 patients." (PMID 34262047, 2021). "For example, inflammatory genes including S100A8 and S100A9 were upregulated in COVID-19 compared to healthy donors." (PMID 34108966, 2021). "This study provides comparative, circulatory expression profiles of DEFA1, S100A8/A9 and MPO in COVID-19 patients with different clinical presentations." (PMID 34746027, 2021). "High serum levels of S100A8/A9 and HMGB1 found in COVID-19 patients upon admission to hospital have been correlated with worse clinical outcomes." (PMID 34948277, 2021). "We found here that genes related to neutrophil activation, including S100A8, S100A9, and S100A12, were expressed at higher levels in monocytes from severe COVID-19 patients than those in mild cases." (PMID 33101705, 2020). "Increased expressions of S100A8, S100A9, and S100A12 calgranulins found in the BALF fluid from COVID-19 patients indicate their potential role in generating the proinflammatory response." (PMID 33335518, 2020). "Thus, the regulatory effect of S100A8 on CYBA and CTSS can be considered a characteristic of COVID-19 severity." (PMID 40362649, 2025).
COVID-19 (continued). "In their study, IFI44L in B cells, S100A8 in monocytes, and NCR2 in natural killer cells were identified as crucial markers that are involved in the innate immune response of COVID-19, while it was also demonstrated that ZFP36L2 in CD4+ T cells can regulate the inflammatory process of COVID-19." (PMID 40163554, 2025). "In HSPCs of COVID-19, late-phase CD14+ monocytes retain elevated levels of inflammatory mediators such as S100A8 and S100A9 relative to both healthy controls and early-phase samples, underscoring their progression toward a more differentiated, pro-inflammatory phenotype." (PMID 41550933, 2025). "Furthermore, S100A8 and S100A9 are also considered crucial therapeutic targets for inflammatory response to COVID-19." (PMID 40362649, 2025). "Thus, uncovering novel treatment approaches targeting the molecular system of ACKR2, S100A8, and S100A9 for COVID-19 is a future research step in our study." (PMID 40362649, 2025). "Increased levels of S100A8, MKI67, HSPA5, LYZ, CTSD, and IGHG1 were observed in COVID-19 patients." (PMID 39026676, 2024). "Our study is the first to demonstrate thatwhile serum S100A8/A9 levels are elevated during severe COVID-19,these levels are not correlated in matched urine samples." (PMID 37787461, 2023). "Furthermore, we demonstrated the important role of some inflammatory genes (such as S100A8 and S100A9) in the pathogenesis of COVID-19 and found that regulators of these critical genes can be unique to cell types and conditions." (PMID 37936693, 2023). "Similarly, for CD14 and CD16 monocyte cells in severe COVID-19, CEBPD and FOS were particularly activated in the two cell types, and CEBPD upregulated S100A8 and S100A9." (PMID 37936693, 2023). "Finally, correlation between S100A6, S100B, S100A8, S100A9, S100A12, and S100P and COVID-19 pathogenesis is discussed." (PMID 35892571, 2022). "Clinical studies revealed high S100A8 and S100A9 serum concentrations as the best predictive biomarkers for critical COVID-19 cases and mortality, indicating that these endogenous ligands of TLR4 amplify also the aberrant innate anti-viral response during SARS-CoV-2 infection." (PMID 35741108, 2022). "In WT cells, S100a8 production is generally suppressed upon TLR4 activation, analogous to clinical studies which show that circulating calprotectin levels remain low in majority of the COVID-19 patients who are asymptomatic or have mild symptoms." (PMID 36172386, 2022). "scRNA-seq results of COVID-19 find that changes of host factors including EN-RAGE, TNFSF14, oncostatin M, ANXA1, FPR1, and S100A8/9 are correlated with disease severity, revealing the possible pathogenesis of severe COVID-19 and potential host therapeutic targets." (PMID 35495713, 2022). "S1 cells exhibited the highest expressions of alarmins S100A8, S100A9, S100A12 and toll-like receptors TLR4 and TLR8, all of which are involved in neutrophil activation and were the most mature neutrophils in both KD and Severe COVID-19 patients." (PMID 36159873, 2022). "With scatterplots, the relationship between S100A8 and CTSL genes and SARS-CoV-2 infection was suggested to be only negatively related to viral gene expression levels in high infections, and all COVID-19–related viral genes, especially N and ORF1ab genes, showed a positive relationship." (PMID 34497809, 2021). "S100A8/A9 proteins were significantly higher in COVID-19 patients (p<0.0001) irrespective of disease severity." (PMID 34746027, 2021). "Additionally, we found that PCs in patients with severe COVID-19 had higher expression levels of inflammation genes (TNFSF10, S100A9, and S100A8) and chemokine-related genes (CCR2 and ITGB7) than those in patients with mild COVID-19." (PMID 33936072, 2021).
COVID-19 (continued). "Further, the deep plasma proteome study of non-severe versus severe COVID-19 patients revealed only 38 differentially expressed proteins, out of which proteins such as FGG, S100A8, VWF, SAA4, SERPIND1, and SERPINA6 were identified to be significantly upregulated in the COVID-19 severe patients." (PMID 33995121, 2021). "Furthermore, blood levels of IL1α, calprotectin (a heterodimer made of S100A8 and S100A9), S100A12, S100B and HGBM1 appear to correlate with COVID-19 severity." (PMID 34293006, 2021). "An additional 8 targets (CXCL6, IFI44, IFI44L, RSAD2, S100A8, SPRR2A, SYNE1, XAF1) are associated with COVID-19 pathogenesis, but do not have therapies targeting them available for potential repurposing." (PMID 34582497, 2021). "These insights suggest S100 proteins could serve as biomarkers for disease severity, prognosis, and therapeutic response; for instance, high levels of S100A8/A9 may indicate severe COVID-19 or pulmonary fibrosis, and S100A12 and S100A8/A9 can help monitor graft rejection in lung transplant patients." (PMID 41164170, 2025). "It has been shown that S100A8 is responsible for the induction of an aberrant neutrophil subset in pathogenesis of COVID-19 through stimulating the TLR4 signaling, which are thought to induce cytokine storm or excessive inflammation, as is observed in severe COVID-19 cases." (PMID 39350339, 2024). "BAL alveolar macrophages from severe COVID-19 patients (n = 23) were characterized by an increased production and release of several pro-inflammatory mediators, such as IL-1β, IL-6, CCL3 and CCL4 and increased expression of IL-1R and S100A8/9 proteins, compared to those from mild COVID-19 patients." (PMID 36941580, 2023). "However, the exact role of S100A8 and S100A9 during this infection is still under investigation and it has still to be clarified how both S100A8/S100A9 mechanistically contribute to the outcome of COVID-19." (PMID 35741108, 2022). "Cluster 12 and 13 report proteins that are increased in all COVID-19 patients but at higher levels in ICU/F patients which are mainly constituted by proteins playing a role in acute inflammatory response (CRP, ORM1, ORM2, SAA1, SAA2, S100A8, S100A9, Serpin A3)." (PMID 36348270, 2022). "Since PU.1 is a master-regulator of myelopoiesis, PIRAT might also contribute to the imbalanced myeloid differentiation trajectories seen in severe COVID-19, independent of S100A8 and A9." (PMID 35998224, 2022). "Finally, we demonstrated that influenza virus infection also induces the expression of S100A7, S100A8, S100A9, and S100A12 in the alveolus chip, a finding that is consistent with recent clinical observations from COVID-19 patients that exhibit late stage lung infections with SARS-CoV-2 virus." (PMID 35396513, 2022). "In addition, we note specific upregulation of alarmins S100A8/S100A9 (i.e., calprotectin) among epithelial cells in the severe COVID-19 group compared to mild or moderate and control counterparts, and even higher expression of S100A9 within SARS-CoV-2 RNA+ cells from those same individuals." (PMID 34352228, 2021). "Although there is no application of alarmin blockade in COVID-19 and comorbidities, previous studies have suggested the therapeutic potential of neutralizing antibodies against S100A8/A9, HMGB1, or histones for the inhibition of pulmonary fibrosis and sepsis-associated ALI/ARDS." (PMID 34682694, 2021). "Moreover, SA100A12, together with S100A8 and S100A9, which are also both released by neutrophils, can activate airway epithelial cells to produce MUC5AC, a major mucin protein in the respiratory tract, partly interoperating the excessive mucus discovered in the necropsy of COVID-19 patients." (PMID 34457122, 2021).
COVID-19 (continued). "In module 2, mono-CD14+ cells in patients with severe COVID-19 exhibited higher expression levels of glycolysis-related genes (LDHA and PKM) and PPP-related genes (PGD and TKT), which may be involved in the proinflammatory response (upregulation of S100A8, S100A9, S100A12, and IL1B)." (PMID 33936072, 2021). "The gut was not an exception and the defensin HD5, the calprotectin S100A8/A9 and the GDF-15 had a specific role both in the gastroenterological manifestation and the prognosis of COVID-19." (PMID 34042528, 2021). "In addition, massive release of S100A8/S100A9 calprotectin (a ligand of TLR4 and RAGE) has been observed in plasma from patients with severe rather than mild COVID-19." (PMID 34471261, 2021).
psoriasis (131 papers, 2007 to 2025). An autoimmune condition characterized by red, well-delineated plaques with silvery scales that are usually on the extensor surfaces and scalp. "Further examination of gene signature in KCs indicated decreased expression of various psoriasis hallmark genes, such as S100a8, S100a9 and Cxcl1 in K14Cre/+Lztr1fl/fl KCs compared to Lztr1fl/fl KCs." (PMID 41162356, 2025). "In an Egyptian case-control study, researchers evaluated S100A8 serum levels and the S100A8 rs3806232 polymorphism to assess their potential association with psoriasis susceptibility and severity." (PMID 40343299, 2025). "It had previously been found that the inflammation-associated proteins S100A8/9 were highly expressed in the lesional skin of patients with psoriasis." (PMID 39480805, 2024). "For example, S100A8 deficiency induces a severe phenotype of psoriasis-like cutaneous inflammation, and rapid synchronous early resorption of the mouse embryo." (PMID 37346040, 2023). "Psoriasis severity is associated with S100A8 expression; moreover, S100A9 is highly expressed in psoriatic skin lesions." (PMID 37891988, 2023). "Accordingly, genes associated with psoriasis, including S100a8, S100a9, Camp, Tnf, Il1b, Il23a, and Ccl2, were strongly downregulated." (PMID 35869084, 2022). "S100a8 and S100a9, which encodes a calcium-binding protein also known as calprotectin, an early biomarker of psoriasis, were among the most up-regulated genes." (PMID 29158586, 2017). "Additionally, the AA genotype demonstrated a significant association with the severity of psoriasis and elevated S100A8 serum concentrations." (PMID 40343299, 2025). "WY14643 treatment significantly downregulated psoriasis‐associated inflammatory cytokines and chemokines (Il17a, Il1b, Cxcl1, Cxcl2, Cxcl3, Cxcl15, and Csf3) as well as the antimicrobial peptides S100a8 and S100a9 in IMQ‐induced skin lesions at the transcriptional level." (PMID 40878384, 2025). "Furthermore, both necroptosis and ferroptosis in keratinocytes have been implicated in psoriasis and IMQ-induced psoriasis-like dermatitis, through the release of inflammatory cytokines such as S100A8, S100A9, HMGB1, IL-33, IL-1β, and IL-6." (PMID 38429278, 2024). "The expression of many genes known to be associated with psoriasis, including Lce3f, Sprr2b, Krt15, S100a8, S100a9, Il17a, Il17f, Il18, Il20, Il22, and Ccl20, was downregulated in the skin of IMQ-treated Camk4−/− mice compared with those of IMQ-treated Camk4+/+ mice." (PMID 35869084, 2022). "After consulting the literature, we found that in psoriasis and cancer diseases, the IL-17 signaling pathway can cause the production of pro-inflammatory factors such as S100a8 and S100a9, thereby promoting the generation of inflammation and the metastasis of cancer cells." (PMID 35741040, 2022). "Similarly, inhibition of NAMPT, PARP, and AIFM1 reduced the transcript levels DEFB4 and S100A8, another inflammation marker associated with psoriasis, while all treatments further reduced LOR and FLR mRNA levels, as did all-trans retinoic acid (ATRA)." (PMID 34748530, 2021). "The study revealed a significant elevation of serum S100A8 levels in patients with psoriasis compared to control subjects, alongside a positive correlation with disease severity." (PMID 40343299, 2025). "A few inflammatory genes that were shared with vulvar lichen sclerosis and psoriasis were S100A8, S100A9 and FABP5." (PMID 41438752, 2025). "Then, we applied IMQ to the cKO and control mice (Gsdmdfl/fl; S100a8+/+) mice on a continuous basis for 4 days to induce psoriasis." (PMID 39717896, 2024). "And we found that S100a8 is mainly expressed in neutrophils and slightly in macrophages in psoriasis-like mouse skin." (PMID 39717896, 2024). "S100A8/A9 (calprotectin) is claimed to be a sensitive biomarker for inflammatory diseases such as rheumatoid arthritis, psoriasis, and vasculitis." (PMID 37110453, 2023).
psoriasis (continued). "The DEGs between IL-17A treated STAT3 mice and WT mice were highly consistent with those observed in psoriasis patients, including S100A8, S100A9, Sprr2, and LCE." (PMID 37465147, 2023). "Surprisingly, S100A9-deficient mice show slight decreases in the response of neutrophils to stimulation with chemoattractant and slight aggravation of psoriasis symptoms compared with control mice, indicating functional differences between S100A8 and S100A9." (PMID 37346040, 2023). "In psoriasis-affected tissues, S100A8 and S100A9 are highly expressed in the basal and spinous layers." (PMID 37891988, 2023). "A series of psoriasis-related genes, such as S100A8, S100A9, KRT6A (keratin 6A), KRT6B, KRT6C, KRT16, and MMP9 (metalloproteinase 9), were also down-regulated." (PMID 35273606, 2022). "According to the expression of neutrophil marker genes, skin tissue domain was colored and showed that PI3 and S100A8, two neutrophil marker genes, are highly expressed in psoriasis patients." (PMID 35281792, 2022). "In GCF, individuals with psoriasis showed higher levels of S100A8, IL-18 and sE-selectin in comparison to healthy individuals, independent of periodontal status." (PMID 35454992, 2022). "In our study, S100A7, S100A8 and S100A9 were significantly involved in the IL-17A pathway, which is strongly implicated in psoriasis pathogenesis." (PMID 36483564, 2022). "RT-PCR analysis showed that the mRNA levels of IL-23 P19, TNF-α, CXCL2 and S100A8 were significantly attenuated in back skin from IMQ-induced psoriasis mice." (PMID 34381369, 2021). "In particular, the host employs S100 family proteins, such as S100A7 protein psoriasis secreted by keratinocytes and S100A8/S100A9 dimer calprotectin secreted by neutrophil granulocytes to sequester zinc locally and extracellularly." (PMID 33028391, 2020). "S100A7, S100A8 and S100A9, calcium-binding proteins, are located in the psoriasis susceptibility locus 4 and are highly expressed at the epidermis of psoriasis skin lesions." (PMID 32194991, 2020). "Throughout inflammatory dermatoses, especially in psoriasis, both S100A8 and S100A9 are highly up-regulated in skin lesions of patients." (PMID 33643287, 2020). "Accordingly, expression of dominant active S100A8-dimers in a model of TNFα-driven psoriasis-like dermatitis accelerated skin inflammation leading to an aggravated phenotype in mice." (PMID 33643287, 2020). "We chose stimuli known to be relevant in the pathogenesis of psoriasis like IL-17A, IL-17F, TNFα, IL-1α, flagellin as well as murine S100A8 as endogenous Toll-like receptor (TLR)-trigger." (PMID 33643287, 2020). "Expression and secretion of two pro-inflammatory molecules of the S100-alarmin family, S100A8 and S100A9, in keratinocytes is a hallmark of psoriasis, which is also characterized by an altered differentiation of keratinocytes." (PMID 33643287, 2020). "Serum concentrations of S100A8/S100A9 are a reliable biomarker for monitoring disease activity in psoriasis but also rheumatoid arthritis, psoriatic arthritis or infections underlining their clinical relevance." (PMID 33643287, 2020). "The general relevance of S100A8/S100A9 expression during psoriasis is confirmed by the fact that inflammation in psoriasis-like skin disease in mice is strongly attenuated after deletion of the S100A9 gene in mice." (PMID 33643287, 2020). "Only scarce data is available on the response of S100A8/A9 protein expression to psoriasis treatment." (PMID 30865695, 2019). "Previous genomic transcriptome studies on the effect of NB-UVB in psoriasis showed downregulation of S100A8 and S100A9 in response to NB-UVB." (PMID 30865695, 2019). "The genes coding for S100A8 and S100A9 are located within the psoriasis susceptibility locus 4 (PSORS4) mapped to chromosome 1q21." (PMID 30865695, 2019). "Only scarce data is available describing the effect of NB-UVB treatment on the expression of S100A8/A9 in skin from patients with psoriasis." (PMID 30865695, 2019).